FOXP2 (forkhead box P2)
Diseases named in the same sentence as FOXP2 in open-access papers (continued):
Sharing a sentence is not in itself a finding about the gene and the disease.
cancer (continued). "AGAP2-AS1 sponged miR-628-5p, which could negatively regulate FOXP2 to affect the cancer growth." (PMID 39124865, 2024). "In addition, FOXP2 was also suggested regulating the progression of cancer cells." (PMID 33718155, 2021). "Also, FOXP2 regulates proliferation and apoptosis in a variety of malignant tumors." (PMID 33117815, 2020). "Although FOXP2 is a transcription factor closely related to neural development, a number of studies have confirmed that FOXP2 is involved in the development of many other tumor tissues, and whether FOXP2 is a tumor suppressor or cancer promoter remains controversial." (PMID 30728054, 2019). "While the ProteinAtlasDatabase indicates that the overall level of FOXP2 factor in twenty selected cancer conditions may vary in both directions, it thus cannot be ruled out that they reflect secondary impact of oncogenesis on FOXP2 transcription and/or translation." (PMID 29725501, 2018). "The overlapping genes included five known cancer driver genes (including HGF, MET, and PIK3R1) and five putative FOXP2 targets, such as MET and PIK3R1, identified by chromatin immunoprecipitation assays in both mice and humans." (PMID 37668356, 2023). "In a number of cancer types, including THCA, we observed that lower FOXP1, FOXP2 and higher FOXP3, FOXP4 levels in cancer tissues when compared with matched normal tissue." (PMID 36203616, 2022). "FOXP2, as a member of the FOX transcription factor family and a suppressor of tumor metastasis in various human cancers, was chosen for subsequent experiments in this study." (PMID 33718155, 2021). "FOXP2 was found to directly bind to and activate the promoter of PHF2 that stimulated the epithelial phenotype of cancer cells." (PMID 33718155, 2021). "Thus, it may be that the tumor suppressor role ascribed to FOXP2 may in fact be indirect, and rather lie within its capacity to normally prevent mesenchymal stem cells from homing into the tumor and/or subsequently activating resident cancer stem cells." (PMID 29725501, 2018). "Additionally, numerous data have shown that FOXP2 functions may further depend upon interactions with a large repertoire of proteins which may have oncological consequences since some are known to behave as oncogenic drivers in cancer (see section 1.3.2)." (PMID 29725501, 2018). "Browsing further blood malignancy conditions identifies FOXP2 as a putative marker for DLBCL, in line with previous observations that FOXP1 is a determinant oncogenic driver in these cancer types." (PMID 29725501, 2018). "Forkhead box P (FOXP) TFs—FOXP1, FOXP2, FOXP3, and FOXP4—are involved in embryonic development, immune disorders, and cancer progression, but FOXP3’s targeting of CD4 + CD25+ regulatory T (Treg) cells and its dual role as an OCG or tumor suppressor in cancers are unclear and controversial." (PMID 38827026, 2024). "Forkhead box P2 (FOXP2) is a member of the FOXP transcription factor (TF) family and contains a C-terminal Winged-helix/Forkhead DNA binding domain, thus playing important roles in embryonic development and cancer progression." (PMID 36331719, 2023). "Additionally, we also identified several genes, including FOXS1, FOXP3, and FOXD2, showed elevated expression in a variety of tumors, while FOXF1, FOXP2, and FOXO1 were downregulated in the majority of cancers." (PMID 37401400, 2023). "EZH2 inhibition also upregulated the protein expression of FOXP2 in human cancer lines H460, H2030, A549, and BEAS-KP, but not in immortalized epithelial cell lines HBEC3KT and BEAS2B." (PMID 36670102, 2023). "The opposite roles of FOXP2 in TC and VEM-resistant cancer cells might be due to the expression changes of upstream or downstream mediators, since a large number of DEGs were identified in the VEM-resistant cells." (PMID 36331719, 2023). "It is worth noticing that most of the studies addressing FOXP2 in cancer entities reported aberrant levels of expression without providing a causative oncogenic event." (PMID 29725501, 2018).
cancer (continued). "One of the FOXP2 down-regulation mechanisms during the EGF-induced EMT might be mediated by the key mesenchymal transcription factor TWIST, whose levels were stimulated by EGF treatment in cancer cells." (PMID 33718155, 2021). "Altogether these proposed steps may explain how a single mutation within FOXP2 may indirectly become a genetic determinant of oncogenesis without affecting FOXP2 simultaneously in six different types of cancers." (PMID 29725501, 2018). "This comparison, while not ruling out a protective role for FOXP2, may be indicative of a more restricted role in preventing cancer initiation." (PMID 29725501, 2018). "For example, the prognostic impact of SOX9, SENP1 and mTOR was limited to ERG positive cancers while FOXA1, MTCO2 and FOXP2 were only prognostic in ERG negative cancers." (PMID 31606028, 2019).
tumor (38 papers, 2015 to 2026). "On the other hand, ATF3, BHLHE40, ZNF263, and FOXP2 transcription factors were strongly associated with GADD45B-low tumor cells." (PMID 37608794, 2023). "Genomic analysis revealed that somatic mutations in FOX genes can be detected in 17.4% of tumor patients, with FOXP2 having the highest mutation rate." (PMID 37401400, 2023). "On the other hand, browsing the Cosmic catalogue returned 531 tumor biopsies displaying a confirmed somatic mutation within the FOXP2 locus." (PMID 29725501, 2018). "Recently, several lines of evidence have revealed that the down-regulation of FOXP2 may be associated with tumor initiation, development, or metastasis." (PMID 31936744, 2020). "Accumulating evidence from prior investigations has demonstrated that FOXP2 is frequently downregulated in diverse tumors, where it exerts tumor-suppressive effects, such as in GC." (PMID 40721413, 2025). "Initially, FOXP2 functions as a tumor suppressor, targeting various tumor inhibitors such as BAX, PTEN, and p16." (PMID 40003882, 2025). "For example, FOXP2, which is also a tumor suppressor, can interact with FOXA2 to inhibit the EMT of cancer cells." (PMID 40003882, 2025). "The top GRNs in primary tumors were TCF4, TAGLN2, FOXK1, and BHLHE41, whereas the top upregulated GRNs in recurrent tumor cells were FOXP2, FOXD1, SIX4, and HMGB1." (PMID 39711559, 2024). "Given the increased metastatic potential of Ezh2 null tumor cells, we tested if FOXP2 overexpression changed migratory capability by transwell migration assays." (PMID 36670102, 2023). "Shared decreased protein-coding genes across all tumor types included FOXP2, GABRA1/2/4/5, NRGN, SST, and SYNPR." (PMID 36865335, 2023). "Due to loss of miR-27a/b-mediated transcriptional regulation, the fusion yielded a truncated FOXP2 protein that was highly expressed in the fusion-carrying tumor." (PMID 37668356, 2023). "To further demonstrate our findings, we collected 15 pairs of CRC paratumour and tumour tissues by endoscopy, and found that FOXP2 was downregulated in the tumour tissues compared to the paratumour tissues according to RT-PCR assay." (PMID 35281860, 2022). "In line with previous results 9, 17, in our study, we found that FOXP2 functions as a tumour suppressor and can be used to predict patient prognosis." (PMID 35281860, 2022). "Evidenced by quantitative Real Time-PCR, only FOXP2 mRNA showed the significantly down-regulation in tumor in 15 matched DTC and adjacent normal tissues." (PMID 36203616, 2022). "We have shown that patients with down-regulated FOXP2 have a higher probability of tumor recurrence." (PMID 36203616, 2022). "Considering the possible tumor specificity of FOXPs and the significant impact of FOXP2 on the prognosis of THCA, we focused on the link between FOXP2 level and TIICs." (PMID 36203616, 2022). "The chi-square test showed that FOXP2 expression was associated with TNM stage and tumour size (P<0.05)." (PMID 35281860, 2022). "FOXP2 promotes tumour progression in triple-negative breast cancer through the mechanisms of targeting specific molecules." (PMID 36160018, 2022). "We found that among 4 members, only low expression of FOXP2 is strongly associated with shorter DFS, higher tumor stage, and more lymph node metastases." (PMID 36203616, 2022). "The stable knockdown of FOXP2 in MCF7 cells increased the number of circulating tumor cells in the blood of tested mice of day 30 groups." (PMID 33718155, 2021). "As a member of the FOXP family, FOXP2 plays a role in promoting cell migration and invasion during tumor development." (PMID 32183046, 2020). "Combining these results, we conclude that miR-9-5p, through directly downregulating FOXP2 and inhibiting proliferation, is a tumor suppressor in GBM." (PMID 31824836, 2019). "In the present study, we demonstrated that FOXP2 was a tumor promoter, and it was able to accelerate the cell cycle and increase the proliferation of GBM cells." (PMID 31824836, 2019).
tumor (continued). "Having established FOXP2 as a direct target of PRC2 in lung epithelial cells, we sought to understand if FOXP2 could drive the phenotypic differences observed in Ezh2 null tumor cells." (PMID 36670102, 2023). "In addition, whole-genome sequencing of the fusion-positive tumor suggested that the FOXP2 fusion was an early event in the tumor." (PMID 37668356, 2023). "As immune regulatory factor, the reduction of FOXP2 may affect tumor microenvironments and immune cells infiltration, enhance tumor immune escape, and promote recurrence." (PMID 36203616, 2022). "Moreover, surgical samples were collected for IHC assays and the results similarly showed that FOXP2 protein was overexpressed in tumour tissues." (PMID 35281860, 2022). "In line with our RT-PCR assay results, we found lower expression of FOXP2 in the tumour tissue." (PMID 35281860, 2022). "The role of FOXP2 in tumor invasion and recurrence was investigated consequently." (PMID 36203616, 2022). "Taken together, FOXP2 may promote THCA invasion and recurrence by influencing tumor microenvironment and affecting the associated immune infiltrating cells." (PMID 36203616, 2022). "Based on the role of Dendritic cells in tumor immunity, reduced expression of Dendritic cells by FOXP2 down-regulation may promote the occurrence of tumor immune escape." (PMID 36203616, 2022). "More importantly, only FOXP2 showed the significant effect on recurrence and tumor staging." (PMID 36203616, 2022). "Several studies have suggested that FOXP2 functions as a tumour suppressor." (PMID 35281860, 2022). "FOXP2 is involved in the occurrence and development of many other tumor tissues, and whether FOXP2 is a tumor suppressor or tumor-promoting gene remains controversial." (PMID 30728054, 2019). "Recent observations have raised a putative tumor-suppressor role for FOXP2." (PMID 29725501, 2018). "FOXP2 may also participate in modulating the expression of various genes involved in tumor signaling pathways, including IGF-1 (insulin-like growth factor 1), NF-ĸB (nuclear factor kappa-light-chain-enhancer of activated B cells), and Wnt." (PMID 30360388, 2018). "While most anatomic systems have been concerned with morphogenetic alterations, neoplasm has not been reported so far as being associated with Foxp2 dysregulation in the mouse." (PMID 29725501, 2018). "Thus, the lower expression of FOXP2, the higher the tumor stage." (PMID 36203616, 2022). "Finally, we identified miR-9-5p inhibit tumor growth in mouse model by reducing FOXP2 expressing." (PMID 31824836, 2019). "Transcriptional regulatory activity of FOXP2 may be modified by the co-factor CtBP1 (described in section 1.3.1 and 3.3.2) and this interaction may have important oncogenic consequences considering the tumor-promoting activity of CtBPs." (PMID 29725501, 2018). "Thus like many transcription factors including FOXP1, FOXP2 may function as either an oncogene or tumor suppressor depending on cellular context." (PMID 27224915, 2016). "Two GRNs, albeit comprising a smaller number of tumor cells, showed high activity for the TCF7L2 regulon (along with KLF8, FOXK1, FOXP2, BACH1) (labeled TCF7L2+) and CTCF (along with MAFG and NR1H) (labeled CTCF+) respectively." (PMID 38645034, 2024). "Two GRNs, albeit comprising a smaller number of tumor cells, showed high activity for the TCF7L2 regulon (along with KLF8, FOXK1, FOXP2, and BACH1) (labeled TCF7L2+) and CTCF (along with MAFG and NR1H) (labeled CTCF+), respectively." (PMID 38968122, 2024).
tumor (continued). "TISIBD was employed to analyze the relationship between FOXP1, FOXP2, FOXP3, and FOXP4 and tumor-infiltrating immune cells in 28 kinds of tumor." (PMID 36203616, 2022). "FOXP1 and FOXP2 fall under the FOXP sub-family (also comprising FOXP3 and FOXP4) which has functions in oncogenic and tumor suppressive pathways." (PMID 32066696, 2020). "For instance, FOXP2 can interact with C-terminal binding protein 1 (CTBP1), a transcriptional corepressor that modulates and targets tumor suppressors expression, such as BAX, PTEN and p16." (PMID 30360388, 2018). "To test whether EZH2/PRC2 regulates FOXP2 expression through its enzymatic activity, we re-expressed EZH2 WT and enzymatic-incompetent F667I mutant EZH2 in the Ezh2 null mouse tumor cells." (PMID 36670102, 2023). "The amount of metastasized tumor cells in the lungs of day 60 groups was also measured by the mRNA levels of human-specific CYCLOPHILIN over mouse-specific Cyclophilin and showed a significant increase in the FOXP2 knockdown group." (PMID 33718155, 2021). "The most down-regulated genes, FOXO1, FOXN3, and FOXP2, were highly expressed in non-tumor cells, indicating that tumor patients may have an inhibition of the normal cellular function." (PMID 41584858, 2026). "We postulated that our low-proliferative miR-181 KO liver tumours may resemble the ppHCC subtype, as miR-181ab1 KO tumours showed increased expression of some genes, such as CBX7 and FOXP2, which were mainly expressed in periportal hepatocytes (periportal genes)." (PMID 35867177, 2022). "The lack of relationship between full length FOXP2 protein expression and either an ABC/non-GCB DLBCL subtype, or BLIMP1 expression, suggests that its expression in DLBCL is unlikely to reflect purely a plasmablastic tumor phenotype." (PMID 27224915, 2016).
neurodevelopmental disorder (17 papers, 2010 to 2025). A behavioral and cognitive disorder with onset during the developmental period that involves impaired or aberrant development of intellectual, motor, or social functions. "The Forkhead box P2 (FOXP2) has been identified as a gene related to neurodevelopmental disorders, and it was also the first gene to be associated with vocal functions in songbirds and rodents." (PMID 36081908, 2022). "The failure to observe any substantial effects of polyglutamine tract reduction on core aspects of FOXP2 function makes it less likely that tract length reductions contribute to risk for neurodevelopmental disorder." (PMID 27933109, 2016). "To clarify the etiological contribution of the rare FOXP2 variants reported to date in individuals with neurodevelopmental disorders, we performed functional characterization of these variants by assaying their effects on a range of molecular properties." (PMID 27933109, 2016). "We examined seven rare FOXP2 variants that have been observed in individuals with neurodevelopmental disorders, including five missense variants, one stop-gain variant, and one frameshift variant." (PMID 27933109, 2016). "Two of the five FOXP2 missense variants reported in individuals with neurodevelopmental disorders lie within or near the leucine zipper domain, which spans residues p.V388-L409." (PMID 27933109, 2016). "By performing detailed functional characterization of rare variants in FOXP2 found in individuals with neurodevelopmental disorders, we confirm the causal role of one recently reported uncharacterized variant and provide further characterization of two further causal variants." (PMID 27933109, 2016). "Interestingly, the NuRD complex plays an important role in the developing brain, apparent from the links of multiple of the core NuRD complex members with neurodevelopmental disorders that are characterized by features that partly overlap with the FOXP2‐associated phenotypes." (PMID 34260143, 2021). "Our results highlight expression of FOXP2 in early human Purkinje cells and cerebellar nuclei neurons, and the vulnerability of these cell populations to neurodevelopmental disorders." (PMID 41236144, 2025). "The HYDIN protein, associated with cilia in the brain, is critical for development of ventricles and brain; and it interacts with other genes like FOXP2 which are well known to be related to neurodevelopmental disorders such as ASD and ADHD45." (PMID 34702870, 2021). "Studies of larger numbers of individuals with FOXP2 proteins with standard-length and reduced-length tracts are therefore necessary to determine if tract length reduction might confer an increased risk for neurodevelopmental disorder or a reduction in linguistic abilities." (PMID 27933109, 2016). "Dysregulation of these miRNAs or of miRNA–FOXP1/FOXP2 interactions by genetic, environmental, or physiological factors, thus, may contribute to language impairments and related neurodevelopmental disorders." (PMID 29345619, 2018). "We find that these tracts are not essential to the core molecular functions of the FOXP2 protein, suggesting that variations in tract length are unlikely to be a highly penetrant cause of neurodevelopmental disorder." (PMID 27933109, 2016). "Finally, we analysed the functional significance of the polyglutamine tracts in FOXP2, since tract length variations have been reported in cases of neurodevelopmental disorder." (PMID 27933109, 2016).
neurodevelopmental disorder (continued). "More thorough phenotypic comparison studies between these distinct neurodevelopmental disorders and functional follow‐up would be required to uncover whether equivalent variants in FOXP1 and FOXP4 directly impact speech and language or whether they have an indirect effect on the function of FOXP2." (PMID 34260143, 2021).